CTNNA1 (catenin alpha 1)
Description:
Associates with the cytoplasmic domain of a variety of cadherins. The association of catenins to cadherins produces a complex which is linked to the actin filament network, and which seems to be of primary importance for cadherins cell-adhesion properties. Can associate with both E- and N-cadherins. Originally believed to be a stable component of E-cadherin/catenin adhesion complexes and to mediate the linkage of cadherins to the actin cytoskeleton at adherens junctions. In contrast, cortical actin was found to be much more dynamic than E-cadherin/catenin complexes and CTNNA1 was shown not to bind to F-actin when assembled in the complex suggesting a different linkage between actin and adherens junctions components. The homodimeric form may regulate actin filament assembly and inhibit actin branching by competing with the Arp2/3 complex for binding to actin filaments. Involved in the regulation of WWTR1/TAZ, YAP1 and TGFB1-dependent SMAD2 and SMAD3 nuclear accumulation (By similarity). May play a crucial role in cell differentiation.
Synonyms: CAP102; MDBS2; MDPT2
Tractability: Small molecule: a structure with a bound ligand is known. Antibody: UniProt places it where antibodies can reach, with high confidence; its Gene Ontology location is reachable by antibodies, with high confidence; the Human Protein Atlas places it where antibodies can reach. PROTAC: UniProt records ubiquitination sites on it; ubiquitination databases record sites on it; its protein half-life has been measured.
Target class: Adhesion
Gene: Protein-coding gene on chromosome 5 (138,610,967 to 138,935,039, forward strand). Ensembl gene ENSG00000044115.
Subcellular location: Cytoplasm, cytoskeleton; Cell junction, adherens junction; Cell membrane; Cell junction; Cytoplasm; Nucleus; Cell membrane (Isoform 3)
Subcellular location (Human Protein Atlas): Cell Junctions; Plasma membrane; Connecting piece; Golgi apparatus; Mid piece; Principal piece; Vesicles
Pathways (Reactome):
Cell-Cell communication: Activation of STAT3 by cadherin engagement; Adherens junctions interactions; CDH11 homotypic and heterotypic interactions; Degradation of CDH1; Regulation of CDH1 Function; Regulation of CDH11 function; Regulation of CDH19 Expression and Function; SRC activates STAT3 in a quantitative manner, through Cadherin-11 (CDH11), RAC1 and gp130 (IL6ST)
Signal Transduction: RHO GTPases activate IQGAPs; VEGFR2 mediated vascular permeability
Developmental Biology: Myogenesis
Gene Ontology:
Molecular function: beta-catenin binding; cadherin binding; gamma-catenin binding; identical protein binding; protein binding; RNA binding; vinculin binding; actin filament binding; cytoskeletal protein binding; protein-containing complex binding; structural molecule activity
Biological process: cellular response to indole-3-methanol; apical junction assembly; cell adhesion; cell migration; cell-cell adhesion; negative regulation of protein localization to nucleus; axon regeneration; gap junction assembly; male gonad development; odontogenesis of dentin-containing tooth; ovarian follicle development; response to estrogen
Cellular component: anchoring junction; catenin complex; cell junction; cell-cell junction; focal adhesion; nucleus; plasma membrane; adherens junction; cytoplasm; cytosol; acrosomal vesicle; actin cytoskeleton; cytoskeleton; flotillin complex; intercalated disc; lamellipodium; plasma membrane protein complex; zonula adherens
Genetic constraint (gnomAD): Loss-of-function variants: 34 observed, 92.13 expected, observed/expected ratio (o/e) 0.37, 90% interval 0.28 to 0.49. The upper end of that interval is the gene's LOEUF score, 0.49, which puts it in group 2 of 6, group 1 being the genes least tolerant of losing a copy. Missense variants: 707 observed, 1,083.6 expected, observed/expected ratio (o/e) 0.65, 90% interval 0.61 to 0.69. Synonymous variants: 365 observed, 394.13 expected, observed/expected ratio (o/e) 0.93, 90% interval 0.85 to 1.01.
Gene-disease validity (ClinGen):
ClinGen rates the evidence that CTNNA1 causes each of these diseases.
hereditary nonpolyposis colon cancer (autosomal dominant): No Known Disease Relationship.
Homologues: Orthologues: chimpanzee CTNNA1 (99% identical), pig CTNNA1 (99% identical), macaque CTNNA1 (99% identical), mouse Ctnna1 (99% identical), rat Ctnna1 (99% identical), dog CTNNA1 (99% identical), guinea pig CTNNA1 (99% identical), rabbit CTNNA1 (99% identical), tropical clawed frog ctnna1 (93% identical), zebrafish ctnna1 (91% identical), Drosophila melanogaster alpha-Cat (61% identical), Caenorhabditis elegans hmp-1 (39% identical). Paralogues in human: CTNNA2 (82% identical), CTNNA3 (59% identical), VCL (22% identical), CTNNAL1 (19% identical).
Diseases named in the same sentence as CTNNA1 in open-access papers:
CTNNA1 is named in the same sentence as 79 diseases in open-access papers, as found by Europe PMC text mining. Sharing a sentence is not in itself a finding about the gene and the disease. The quoted sentences say what the papers report.
gastric cancer (18 papers, 2016 to 2025). A primary or metastatic malignant neoplasm involving the stomach. "Loss-of-function variants of the CTNNA1 gene have been described predominantly in patients with gastric cancer, and more rarely in patients with breast cancer." (PMID 39684352, 2024). "CDH1 is a suppressor gene of gastric cancer, Although the variation in CTNNA1 was not initially noticed since it did not induce carcinogenesis 49, further studies have shown that CTNNA1 is indeed a susceptibility gene for gastric cancer." (PMID 36741258, 2023). "At present, pathogenic mutations in CTNNA1 explain < 2% of the HDGC family, while previous studies have detected at least 25 mutations in CTNNA1 in gastric cancer." (PMID 36741258, 2023). "Genetic testing technologies have become more efficient over the years, also enabling the discovery of other susceptibility genes for gastric cancer, such as CTNNA1 among the most important genes." (PMID 35887173, 2022). "In 2013 a loss of Alpha-Catenin expression caused by germline PVs in the CTNNA1 gene and somatic silencing of the wildtype allele was found in gastric cancer samples of a large HDGC pedigree." (PMID 33322525, 2020). "Most of the patients had stage III gastric cancer, suggesting that CTNNA1 mutations may correlate with gastric cancer pathogenesis and even advanced cancer." (PMID 36741258, 2023). "Repeated observation of the cohort of gastric cancer patients without CDH1 mutations discovered CTNNA1 mutations (2/28), supporting the hypothesis that pathogenic CTNNA1 variants are the rare causes of gastric cancer." (PMID 36741258, 2023). "Therefore, the quoted lifetime gastric cancer risk in CTNNA1 carriers will also likely decrease as more families are identified." (PMID 37165697, 2023). "Germline mutations of CTNNA1 play a role in a few gastric cancer cases or families 50-56." (PMID 36741258, 2023). "If there is a family history of DGC along with a PV in CDH1 or CTNNA1, then risk-reducing total gastrectomy should be considered, with preoperative endoscopy performed to identify whether gastric cancer has already developed." (PMID 37165697, 2023). "They concluded that the overall risk of gastric cancer for CTNNA1 LOF carriers may be lower than expected." (PMID 33868605, 2021). "Pathogenic variants of CDH1 and CTNNA1 have been linked to gastric cancer (GC) and lobular breast cancer (LBC)." (PMID 40551901, 2025). "Hereditary diffuse gastric cancer syndrome (HDGC) is the most common inherited entity related to GC, involving a germline mutation in CDH1 and much less frequently in CTNNA1, with a cumulative risk of GC of up to 80%." (PMID 32842532, 2020). "A cohort study of 207 patients with gastric cancer (161 families) detected one pathogenic CTNNA1 variant in two patients of the same family 57, demonstrating that CTNNA1 is most likely a suppressor gene of gastric cancer." (PMID 36741258, 2023). "Current gastric surveillance recommendations from the International Gastric Cancer Linkage Consortium (IGCLC) for carriers of a PV in CDH1 or CTNNA1 help inform this decision and are based on family history of DGC121." (PMID 37165697, 2023). "As another member of E-cadherin-catenin complex, the methylation state of CTNNA1 in gastric cancer warrants further research." (PMID 36741258, 2023). "HDGC is associated with PVs in either the CDH1 or CTNNA1 gene and confers the highest risk of DGC amongst all of the known hereditary gastric cancer risk syndromes." (PMID 37165697, 2023). "Although a close relationship between CTNNA1 mutations and gastric cancer has been established, and some diagnosis and treatment guidelines have been proposed 50, the specific effect of CTNNA1 on gastric cancer pathogenesis remains elusive." (PMID 36741258, 2023).
gastric cancer (continued). "HDGC is the most common cancer predisposition for gastric carcinoma and is caused by germline variants in CDH1 and CTNNA1." (PMID 36612313, 2023). "In line with our findings, brain tumors have previously been reported in gastric cancer families with causative germline alterations in CDH1 and other (suspected) tumor suppressor genes, e.g. ATM, CTNNA1, and SDHB." (PMID 33929593, 2021). "CDH1 and CTNNA1 remain as the main genes for hereditary gastric cancer." (PMID 38796558, 2024). "A retrospective study of CDH1 mutant-negative patients suspected of HDGC found loss of CTNNA1 in diffuse gastric cancer, suggesting that CTNNA1 may be a new susceptibility gene for gastric cancer." (PMID 36741258, 2023). "On the other hand, a decreased expression levels of catenin alpha-1 (P35221; CTNNA1 or Renal carcinoma antigen NY-REN-13) is commonly seen in gastric carcinoma patients." (PMID 30379886, 2018). "Familial non-hereditary gastric cancer (FNHGC) serves as an umbrella term for families with two or more cases of gastric cancer in first- or second-degree relatives, but without identified CDH1, CTNNA1, or other high-penetrance germline mutations." (PMID 41097736, 2025). "Next-generation sequencing of unexplained young or familial gastric cancer cases without CDH1 mutations revealed that CTNNA1, MYD88, and MAP3K6 had deleterious mutations associated with gastric cancer." (PMID 36741258, 2023). "CTNNA1, along with other MAPK related genes, have been proved to be involved in gastric cancer." (PMID 27530161, 2016). "If there is no family history of gastric cancer, carriers of a PV in CDH1 or CTNNA1 may consider either risk-reducing total gastrectomy or yearly surveillance." (PMID 37165697, 2023).
breast carcinoma (14 papers, 2015 to 2024). "There is also little data on the penetrance of diffuse gastric carcinomas and breast carcinomas in CTNNA1 loss-of-function carriers." (PMID 35448173, 2022). "Recently, a genetic examination of more than 150,000 individuals revealed that 33 (0.02%) had a CTNNA1 loss-of-function mutation and of those only 4 (12%) had diffuse gastric cancer, but 22 (67%) had breast cancer." (PMID 35448173, 2022). "Pathogenic germline variants in CDH1 and CTNNA1 lead to a high prevalence of diffuse gastric cancer and breast cancer in carrier families." (PMID 33322525, 2020). "The deletion of CTNNA1 effects the loss of cell-to-cell adhesion, enhancing the growth and mobility of breast cancer cells." (PMID 32489334, 2020). "The association of CTNNA1 pathogenic variants with increased LBC risk is also still inconclusive; although some studies have been associating CTNNA1 and breast cancer, this association remains to be clarified since the subtype of these cancers was not specified." (PMID 37686589, 2023). "Furthermore, EMT is associated with metastasis in liver cancer 93, breast cancer 94, and endometrial cancer 95; however, no studies have demonstrated that EMT-related tumor metastasis in liver or breast cancer is associated with CTNNA1." (PMID 36741258, 2023). "CMTM7 can interact with Catenin Alpha 1 to regulate Wnt/β-catenin signaling to inhibit breast cancer progression and be a novel target for breast cancer." (PMID 38223763, 2024). "This suggests that CTNNA1 plays a role in the anti-cancer effect of LSD1 in luminal breast cancer, while TRIM37 inhibits this anti-cancer effect." (PMID 36741258, 2023). "The loss of CTNNA1 releases the suppression of the NF-κB pathway in breast cancer, while a CTNNA1 deletion attenuates the tumor suppressive effect of Beclin-1." (PMID 36741258, 2023). "Catenin alpha 1 (CTNNA1) and mediator complex subunit 12 (MED12) have been shown to associate with breast cancer." (PMID 38137912, 2023). "The association of CTNNA1 pathogenic variants with high risk of LBC is also still uncertain; therefore, breast cancer surveillance should be considered based on personal and family history." (PMID 37686589, 2023). "In the current study, we revealed a feedback loop formed by miR-182-5p/CMTM7/CTNNA1/CTNNB1/TCF3 in breast cancer progression." (PMID 36829181, 2023). "In another recent research on individuals with gastric or breast cancer, it had been revealed that there are several loss-of-function (LOF) and missense variants in the CTNNA1 gene." (PMID 33868605, 2021). "Although data on families with germline PVs in CTNNA1 are scarce, an increased risk for DGC and breast cancer (BC) has been reported, even though the histologic subtype of BC cannot be specified until now." (PMID 33322525, 2020). "We observed heterozygous loss of several cancer‐associated genes, including the CTNNA1 (catenin (cadherin‐associated protein), alpha 1) and APC tumor suppressor genes in the breast cancer." (PMID 26432421, 2015). "Besides, the co-localization of CMTM7 and CTNNA1 in breast cancer cells was verified using immunofluorescence." (PMID 36829181, 2023). "A feedback loop formed by miR-182-5p/CMTM7/CTNNA1/CTNNB1/TCF3 may play a critical role in breast cancer." (PMID 36829181, 2023). "In summary, our study uncovered the existence of the miR-182-5p/CMTM7/CTNNA1/CTNNB1/TCF3 regulation loop in breast cancer, which may provide novel targets and promising strategies for breast cancer therapy." (PMID 36829181, 2023). "In conclusion, CTNNA1 may inhibit breast cancer deterioration and promote cell apoptosis and tumor enlargement, which may be related to Rho/Rock." (PMID 36741258, 2023). "For example, decreased expression CTNNA1 and CTNNB1 corresponds to the progression of in situ breast carcinoma to invasive carcinoma." (PMID 36741258, 2023).
breast carcinoma (continued). "We identified a feedback loop with the composition of miR-182-5p, CMTM7, CTNNA1, CTNNB1 (β-catenin), and TCF3, which play essential roles in breast cancer progression." (PMID 36829181, 2023). "The conclusion that CTNNA1 suppress cancer metastasis in bladder cancer via EMT provides novel insights into the role of CTNNA1 in many other carcinomas such as liver cancer, breast cancer, and endometrial cancer." (PMID 36741258, 2023). "CRISPR/Cas9 knockdown of CTNNA1 and CDH1 reverses the inhibitory effect of Beclin-1 on breast cancer cell proliferation." (PMID 36741258, 2023). "In the current study, we successfully targeted dysregulated CTNNA1, CTNNB1, TLN1, VCL, PXN, and ACTN1 genes by delivering respective siRNAs with the help of nano-sized CA particles in breast cancer cells as well as in a murine breast cancer model." (PMID 31269666, 2019). "CTNNA1 expression significantly decreases in basal-like breast cancer with negative CDH1, which shows a negative correlation with the level of TNF-β and Re1B." (PMID 36741258, 2023). "Theα-catenin coding genes, CTNNA1, CTNNA2 and CTNNA3, participate carcinogenesis of multiple cancers, such as laryngeal carcinomas, oropharyngeal squamous cell carcinomas and breast cancer." (PMID 26882563, 2016).
diffuse gastric cancer (9 papers, 2020 to 2024). "A deleterious CTNNA1 germline variant was found in 0.7% (1/141) of diffuse gastric cancer patients meeting the 2020 IGCLC criteria, as compared to the rate of 2.8% of CDH1 deleterious variants found by us in this setting." (PMID 37686589, 2023). "In addition, we identified a variant within a gene encoding another alpha catenin, CTNNA1, which has recently been categorized as a predisposition gene for Hereditary Diffuse Gastric Cancer." (PMID 37345113, 2023). "Familial diffuse gastric cancer and hereditary diffuse gastric cancer are the most recognizable, familial gastric cancer caused by APC, CDH1, and CTNNA1 gene mutations, respectively." (PMID 38649672, 2024). "Hereditary diffuse gastric cancer (HDGC) is caused by germline pathogenic variants in the CDH1 and CTNNA1 genes and is characterized by a high prevalence of diffuse gastric cancer and lobular breast cancer." (PMID 37686589, 2023). "Hereditary diffuse gastric cancer (HDGC) is an autosomal dominant cancer syndrome defined by germline CDH1 or, occasionally, CTNNA1 variants in either an isolated individual with diffuse gastric cancer (DGC), or in a family with one or more cases." (PMID 35008338, 2021). "The three primary familial gastric cancers include hereditary diffuse gastric cancer, familial intestinal gastric cancer and gastric adenocarcinoma and proximal polyposis of the stomach, caused by germline mutations in genes such as CDH1, CTNNA1 and APC." (PMID 34359744, 2021). "Hereditary diffuse gastric cancer (HDGC) is an autosomal dominant inherited cancer syndrome that has been associated with a mutation of the CDH1, and rarely the CTNNA1 gene, respectively." (PMID 35448173, 2022). "Hereditary diffuse gastric cancer is autosomal dominant that alters the E-cadherin genes (CDH1) and beta-catenin (CTNNA1)." (PMID 39335195, 2024).